MIR567 (microRNA 567)
Synonyms: hsa-mir-567; MIRN567
Gene: MicroRNA gene on chromosome 3 (112,112,801 to 112,112,898, forward strand). Ensembl gene ENSG00000207940.
Gene Ontology:
Biological process: miRNA-mediated post-transcriptional gene silencing
Diseases named in the same sentence as MIR567 in open-access papers:
MIR567 is named in the same sentence as 2 diseases in open-access papers, as found by Europe PMC text mining. Sharing a sentence is not in itself a finding about the gene and the disease. The quoted sentences say what the papers report.
cancer (1 paper, 2017). A tumor composed of atypical neoplastic, often pleomorphic cells that invade other tissues. "Other MS loci display marked cancer-type specificity, for example, MSI events within the 5′ UTR region of ZNF738, C10orf140, ZNF271 and RAB28 are specific to COAD tumours, whereas those in EBP, TMEM182, MIR567 and MEIS1 are absent or substantially depleted in STAD compared to COAD and UCEC tumours." (PMID 28585546, 2017).
MIR567 also shares sentences with these, for which no sentence is quoted: tumours (1 paper).